SLC7A6 (solute carrier family 7 member 6)
Description:
Heterodimer with SLC3A2, that functions as an antiporter which operates as an efflux route by exporting cationic amino acids such as L-arginine from inside the cells in exchange with neutral amino acids like L-leucine, L-glutamine and isoleucine, plus sodium ions and may participate in nitric oxide synthesis. Also exchanges L-arginine with L-lysine in a sodium-independent manner. The transport mechanism is electroneutral and operates with a stoichiometry of 1:1. Contributes to ammonia-induced increase of L-arginine uptake in cerebral cortical astrocytes leading to ammonia-dependent increase of nitric oxide (NO) production via inducible nitric oxide synthase (iNOS) induction, and protein nitration (By similarity). May mediate transport of ornithine in retinal pigment epithelial (RPE) cells. May also transport glycine betaine in a sodium dependent manner from the cumulus granulosa into the enclosed oocyte (By similarity).
Synonyms: y+LAT-2; KIAA0245; LAT3; LAT-2
Tractability: Antibody: UniProt places it where antibodies can reach, with high confidence; its Gene Ontology location is reachable by antibodies, with high confidence; UniProt predicts a signal peptide or a membrane-spanning region. PROTAC: its protein half-life has been measured.
Gene: Protein-coding gene on chromosome 16 (68,264,233 to 68,301,823, forward strand). Ensembl gene ENSG00000103064.
Subcellular location: Cell membrane
Subcellular location (Human Protein Atlas): Vesicles; Plasma membrane
Pathways (Reactome):
Hemostasis: Basigin interactions
Transport of small molecules: Amino acid transport across the plasma membrane
Gene Ontology:
Molecular function: arginine binding; basic amino acid transmembrane transporter activity; L-arginine transmembrane transporter activity; L-lysine:L-arginine antiporter activity; protein binding; amino acid transmembrane transporter activity; transmembrane transporter activity
Biological process: amino acid import across plasma membrane; L-arginine transmembrane transport; L-leucine transport; neutral amino acid transport; ornithine transport; amino acid transmembrane transport; glycine betaine transport; nitric oxide biosynthetic process; L-lysine transmembrane transport; transmembrane transport
Cellular component: plasma membrane; transmembrane transporter complex; membrane
Genetic constraint (gnomAD): Loss-of-function variants: 25 observed, 46.36 expected, observed/expected ratio (o/e) 0.54, 90% interval 0.39 to 0.75. The upper end of that interval is the gene's LOEUF score, 0.75, which puts it in group 3 of 6, group 1 being the genes least tolerant of losing a copy. Missense variants: 506 observed, 659.76 expected, observed/expected ratio (o/e) 0.77, 90% interval 0.71 to 0.82. Synonymous variants: 270 observed, 262.74 expected, observed/expected ratio (o/e) 1.03, 90% interval 0.93 to 1.14.
Homologues: Orthologues: chimpanzee SLC7A6 (100% identical), macaque SLC7A6 (98% identical), dog SLC7A6 (91% identical), guinea pig SLC7A6 (90% identical), rat Slc7a6 (90% identical), mouse Slc7a6 (89% identical), zebrafish slc7a6 (72% identical), tropical clawed frog slc7a6 (72% identical), Drosophila melanogaster mnd (47% identical), Drosophila melanogaster CG1607 (43% identical), Caenorhabditis elegans aat-1 (42% identical), Caenorhabditis elegans aat-2 (40% identical), and 7 more. Paralogues in human: SLC7A7 (71% identical), SLC7A8 (46% identical), SLC7A5 (46% identical), SLC7A10 (43% identical), SLC7A11 (43% identical), SLC7A9 (40% identical), SLC7A13 (30% identical), SLC7A1 (24% identical), SLC7A2 (24% identical), SLC7A3 (23% identical), SLC7A4 (21% identical), SLC7A14 (21% identical).
Diseases named in the same sentence as SLC7A6 in open-access papers:
SLC7A6 is named in the same sentence as 31 diseases in open-access papers, as found by Europe PMC text mining. Sharing a sentence is not in itself a finding about the gene and the disease. The quoted sentences say what the papers report.
breast carcinoma (3 papers, 2022 to 2025). "Interestingly, SLC7A6 and SLC1A5 have been shown to be targets of driver genes implicated in tumorigenesis, such as c-Myc in breast cancer, lung small cell carcinoma, colorectal carcinoma, glioblastoma, and HCC." (PMID 39062801, 2024). "According to the literature review, USP3 promotes GC cell migration and invasion; SLC7A6 hasn’t been reported in studies related to cancer; IGF2BP1 accelerates GC progression; and TKT facilitates breast cancer metastasis." (PMID 35739527, 2022).
colorectal cancer (3 papers, 2023 to 2025). A primary or metastatic malignant neoplasm that affects the colon or rectum. "The results reveal that most of the identified essential genes were compatible with the colorectal cancer cell lines obtained from DepMap and that these genes, with the exception of EBP, LSS, and SLC7A6, could generate a high level of cell death when knocked out." (PMID 37205704, 2023).
hepatocellular carcinoma (2 papers, 2023 to 2025). A malignant tumor that arises from hepatocytes. "Interestingly, expression of Slc7a6 is associated with the development of hepatocellular carcinoma, presumably by providing sufficient amounts of amino acids necessary for cell growth, which was also proposed for other Slc members." (PMID 40627780, 2025). "SLC7A6 is upregulated in hepatocellular carcinoma, leading to a significant increase in the uptake of amino acids, which further activates the mTOR signaling cascade and promotes tumor formation." (PMID 37940982, 2023). "Downregulation of SLC7A6 inhibits the proliferation and invasion of hepatocellular carcinoma." (PMID 37940982, 2023).
Aminoaciduria (1 paper, 2025). An increased concentration of an amino acid in the urine. "The review highlighted 9 genes associated with aminoacidurias, including SLC3A1 (rBAT), SLC7A9 (bo,+AT), SLC6A19 (BoAT1), SLC7A7 (y+LAT1), SLC7A6 (y+LAT2), SLC36A2 (PAT-2), SLC6A20 (SIT-1), SLC6A18 (BoAT3), and SLC1A1 (EAAT3)." (PMID 41142409, 2025).
bladder cancer (1 paper, 2023). "We further validated that SLC7A6 was significantly up-regulated in cisplatin resistant bladder cancer cells versus cisplatin sensitive bladder cancer cells while the expression of SLC7A6 in CD8 + T cells remained relatively at minimum level." (PMID 37582769, 2023). "Given that SLC7A6 was the only identified SLC family member which has the possibility for methionine transportation, we further discussed the role of SLC7A6 in cisplatin resistant bladder cancer." (PMID 37582769, 2023).
glioma (1 paper, 2025). A benign or malignant brain and spinal cord tumor that arises from glial cells (astrocytes, oligodendrocytes, ependymal cells). "For instance, in U87-MG glioma and A549 cells, alanine uptake is facilitated by SNAT1, SNAT2, SNAT5, SLC6A15 (B0AT2), SLC7A6 (y+LAT2), SLC1A4 (ASCT1), and SLC1A5 (ASCT2), and many of these transporters are also involved in glutamine transport." (PMID 40716744, 2025).
Hyperammonemia (1 paper, 2022). An increased concentration of ammonia in the blood. "This review focuses on the effects of hyperammonemia on the two glutamine carriers located in the astrocytic membrane: Slc38a3 (SN1, SNAT3) and Slc7a6 (y + LAT2)." (PMID 35733937, 2022).
neuroblastoma (1 paper, 2016). Neuroblastoma (NB) is the most common solid, extracranial childhood tumor. "Our findings that high levels of expression of PRPS2, SDC1 and also SLC7A6 are associated with poor clinical outcome in neuroblastoma, and that PRPS2 and SDC1 are important in proliferation, suggest that these genes may facilitate tumor progression in MYC- and MYCN-driven cancers." (PMID 27448979, 2016).
ovarian carcinoma (1 paper, 2023). A malignant neoplasm originating from the surface ovarian epithelium. "Other transporters not investigated in the present study may compensate for the loss of SLC7A6, contributing to the maintenance of cisplatin resistance of ovarian cancer." (PMID 37940982, 2023). "Collectively, results of the present study demonstrated that baicalein improves the sensitivity of ovarian cancer cells to cisplatin via inhibiting CirSLC7A6/miR-2682-5p/SLC7A6, and further inactivating PI3K/Akt/mTOR and Erk/p38 MAPK pathways." (PMID 37940982, 2023). "Results of the present study uncovered a novel molecular mechanism that baicalein acts as a cisplatin sensitizer, via inhibition of CirSLC7A6/miR-2682-5p/SLC7A6 in ovarian cancer." (PMID 37940982, 2023). "CirSLC7A6 may affect the uptake of amino acids, resulting in the chemoresistance of ovarian cancer cells via suppression of miR-2682-5p and activation of SLC7A6." (PMID 37940982, 2023). "Notably, the effects of SLC7A6 on the chemoresistance of ovarian cancer are yet to be fully elucidated." (PMID 37940982, 2023). "In addition, baicalein cooperating with cisplatin suppresses MMP2 protein expression and cell metastasis of resistant ovarian cancer cells, through regulation of CirSLC7A6/miR-2682-5p/SLC7A6." (PMID 37940982, 2023). "Notably, cisplatin and baicalein may suppress MMP2 protein expression and cell metastasis of resistant ovarian cancer through regulating the CirSLC7A6/miR-2682-5p/SLC7A6 axis." (PMID 37940982, 2023).
pancreatic cancer (1 paper, 2022). "SLC7A6 has also been shown in murine models to regulate glutamine-dependent mTOR activation and decrease sensitivity in pancreatic cancer, leading to the hopes of using it as a therapeutic target for pancreatic cells." (PMID 35967756, 2022).
virus infection (1 paper, 2025). "Obviously, the response of the Slc7a6 to viral infection implied its potential role in the process of BmNPV replication through arginine transport." (PMID 40627780, 2025).
cancer (11 papers, 2012 to 2025). A tumor composed of atypical neoplastic, often pleomorphic cells that invade other tissues. "A particular interest is the SLC7A6 gene, which encodes LAT2, a key glutamine transporter, which has been implicated in cancers." (PMID 35967756, 2022). "The SLC7A6 (solute carrier 7 member of this family of genes) has known functions in the transport of leucin, being involved in promoting cell growth in many cancers and podocyte development." (PMID 26053098, 2015). "Two other sodium-independent large amino acid transporters, SLC43A1 and SLC43A2 are also absent, leaving SLC6A15 encoding a known transporter of BCAA found in the mammalian brain, and SLC7A6, an antiporter exporting Arg and Lys in exchange for Leu, Ile and Gln also expressed in brain and cancers." (PMID 37918802, 2023). "The differential expression of SLC7A6 in CD8 + T cells, treatment naive BCa cells and cisplatin resistant BCa cells suggest that cisplatin resistance cancer cells may outcompete T cells for the consumption of methionine via SLC7A6 to overcome cisplatin resistance." (PMID 37582769, 2023). "We found that the cancer patient treatment-relevant relation between PELO and FOCAD, or the experimentally identified interactions between SLC7A2 and SLC7A1, or SLC7A6 and SLC7A1 were best predicted upon combinatorial normalization (Dataset EV1)." (PMID 40263591, 2025). "Then, the top five higher binding energy ginsenosides were used for docking with other SLC transporters, including SLC7A5, SLC7A6, LCN2, and SLC7A9 cancer-related targets, as well as BSG due to its involvement in amino acid transport." (PMID 40566559, 2025). "On the other hand, SLC7A6 and SLC25A19 play crucial roles in cancer by affecting amino acid transport, energy metabolism, and potential therapeutic targets." (PMID 37737478, 2023). "In addition, three members of solute carrier family 7, a family of amino acid transporters, SLC7A1, SLC7A11 and SLC7A6, negatively correlated with miRNA 143–145 cluster, are reported as up-regulated in tumor cells due to the demand for increased amino acid transport during cancer progression." (PMID 23028787, 2012). "Additionally, an analysis of cancer stages revealed a significant correlation between the expression levels of SLC3A2, BSG, SLC7A5, SLC7A6, LCN2, and SLC7A9 and the pathological stages of ACC, with p-values of 0.28, 0.468, 0.00799, 0.0237, 0.0359, 0.264, 0.193, 0.81, and 0.0246, respectively." (PMID 40566559, 2025). "Both silencing MAT2A and SLC7A6 could decreased the cell proliferation rate of BCa cells, while MAT2A silencing significantly contributes to the cisplatin sensitivity than SLC7A6 in cisplatin resistant cancer cells." (PMID 37582769, 2023).
tumor (8 papers, 2012 to 2024). "RT-qPCR and immunohistochemistry were used to detect the expression of CirSLC7A6, miR-2682-5p, and SLC7A6 in tumor tissues, and western blot analysis was carried out to measure protein expression levels." (PMID 37940982, 2023). "RT-qPCR and immunohistochemistry were used to detect the expression of CirSLC7A6, miR-2682-5p and SLC7A6 in tumor tissues." (PMID 37940982, 2023). "Conversely to SLC38A3, upregulation of SLC38A1, SLC7A6, and SLC1A5 transporters in HCC tumors was associated with decreased overall patient survival, with SLC1A5 being the most significantly associated with tumor aggressiveness." (PMID 39062801, 2024). "We also validated in our TMA cohort that only SLC7A6 negatively correlated with CD8, indicating that high expression of SLC7A6 in tumor microenvironment restricted infiltration of CD8 + T cells." (PMID 37582769, 2023).
infection (4 papers, 2011 to 2025). The state of being infected such as from the introduction of a foreign agent such as serum, vaccine, antigenic substance or organism. "As observed for silencing of Slc7a6 with dsRNA, deficiency in intracellular arginine inhibited BmNPV infection in Slc7a6KO cells, illustrated by quantification of vp39 mRNA, viral DNA load assessment, and viral titer measurements." (PMID 40627780, 2025). "Moreover, knockdown of Slc7a6 in BmN cells and subsequent infection with BmNPV revealed a significant decrease in virus vp39 expression (48 and 72 hpi), viral DNA load (72 hpi), and viral titer (72 hpi) in the later stages of infection." (PMID 40627780, 2025). "Thus, a limiting role for Slc7a6 in the regulation of growth or proliferation is not unprecedented and could be extended to virus replication and virion production in the silkworm/BmNPV infection model." (PMID 40627780, 2025).
SLC7A6 also shares sentences with these, for which no sentence is quoted: adrenocortical cancer (1 paper); brain cancer (1); colon cancer (1); epilepsy (1); esophageal cancer (1); gallbladder cancer (1); gastric cancer (1); glioblastoma (1); hemophagocytic lymphohistiocytosis (1); kidney cancer (1); liver cancer (1); lung carcinoma (1); lung small cell carcinoma (1); lysinuric protein intolerance (1); Obesity (1); prostate carcinoma (1); skin cancer (1).